SPRY1 (sprouty RTK signaling antagonist 1)
Diseases named in the same sentence as SPRY1 in open-access papers (continued):
Sharing a sentence is not in itself a finding about the gene and the disease.
cancer (27 papers, 2008 to 2025). A tumor composed of atypical neoplastic, often pleomorphic cells that invade other tissues. "Focusing on the mRNA expression in the stromal fibroblasts, we found that Spry2 and Spry4 are both greatly downregulated, but curiously, Spry1 is upregulated in the cancer fibroblasts." (PMID 38600092, 2024). "Recent studies have shown that miR-21-5p contributes to the proliferation, migration, and apoptosis of cancer cells with the concomitant degradation of SPRY1." (PMID 38491475, 2024). "GSEA analysis and SPRY1 showed a positive correlation to genes associated with EGFR signaling, and cancer proliferation." (PMID 35910677, 2022). "The transcriptional expression of RP2, NFIA and SPRY1 in four cancer grades was significantly higher than that of the normal." (PMID 36035369, 2022). "The associated cancer functional states of hsa-mir-21 predicted target genes (RP2, NFIA, SPRY1 and TGFBI) was first revealed." (PMID 36035369, 2022). "The expression of Spry1 in human CM was initially explored using publicly available cancer gene expression profiling and transcriptome sequencing data." (PMID 32444628, 2020). "Taking in consideration all of these reports and our findings, the mechanism by which SPRY1 acts in a protective and/or oncogenic role in different cancers is yet to be defined." (PMID 31357584, 2019). "Previous research has shown that the levels of Spry1 and Spry2 are decreased in cancers of the breast, lung, liver, and prostate correlating to poor patient prognosis." (PMID 28196140, 2017). "Majority of the cancer samples demonstrated upregulation of SPRY1 and SPRY2 transcripts as compared with adjacent controls." (PMID 26434583, 2016). "Among the seven cancer cell lines studied, Spry1 was expressed lower in four cell lines and higher in one as compared with the control." (PMID 23251157, 2012). "This all strengthens our conclusion that SPRY1 acts as an angiogenesis inhibitor and makes it an interesting target for future cancer therapies." (PMID 20813052, 2010). "Therefore, we mined the database and confirmed that expression of both Spry2 and Spry4 is downregulated, while Spry1 is upregulated in the cancer fibroblasts of the 4T1 model, similar to that in the human cancer." (PMID 38600092, 2024). "Combined with existing studies 33,34 and our findings, we speculate that the function of SPRY1 in KIRC may affect cancer cells by regulating cell cycle, cell proliferation and cell apoptosis." (PMID 36035369, 2022). "In carcinoma, the published data show that Spry1 is suppressive in breast, prostate, and thyroid." (PMID 34769378, 2021). "SPRY1 has already been correlated to different cancers, but the published data are conflicting." (PMID 31357584, 2019). "Moreover, Spry1 capability to inhibit growth and proliferation of cancer cells has been explored by some investigators." (PMID 24932220, 2014). "Taken together, while both Spry1 and Spry2 were moderately expressed in the normal ovarian cells employed as the control, alterations in the expression of Spry1 and/or Spry2 were found across all cancer cells studied." (PMID 23251157, 2012). "Likewise, the role of Spry proteins, mainly Spry1 and Spry2, in cancer has also been investigated." (PMID 28196140, 2017). "Additionally, Spry1 expression has been shown to be modulated in a variety of cancers." (PMID 25937961, 2013). "Spry proteins, in particular Spry1, Spry2, and Spry4 isoforms that may have an important role in controlling growth signals, are evidently deregulated in some pathological conditions including cancer." (PMID 23251157, 2012). "Interestingly, many of the DMGs identified had multiple roles and several were potential cancer biomarkers or were previously shown to be implicated in various types of cancers, including ABLIM1, ADAM12, ARHGEF4, FBLN2, ITGA6, LRPAP1, Ly9, NT5E, PITPNC1, PLCG1, OBSCN, RHOH, SPTBN1, SPOCK2 and SPRY1." (PMID 41159936, 2025).
cancer (continued). "An inhibitory effect of SPRY1 on angiogenesis, which is induced by PI3K/AKT activation in cancer cells, has been demonstrated previously." (PMID 38491475, 2024). "The transcriptional expression of RP2, NFIA, SPRY1 and TGFBI in four cancer stages was significantly higher than that of the normal." (PMID 36035369, 2022). "Previous studies showed the pro-angiogenic properties of endogenous miR-21-5p and cancer cell derived-miR-21-5p to be dependent on KRIT1 and Spry1 in vessel endothelial cells." (PMID 35346324, 2022). "Our in-silico validation took into consideration a large number of cancer types, and showed that median FREM2 and SPRY1 expression were comparable among the different cancer types." (PMID 31357584, 2019). "On the other hand, there was no differential expression of NCL, FREM2, and SPRY1 genes in the sEVs of cancer cell lines and astrocytes." (PMID 33187334, 2020). "The SPRY1 role in cancer development is believed to be through acting as a negative feedback inhibitor of RTK signaling (pathways that are commonly altered in many cancers), and as an inductor of cellular senescence." (PMID 31357584, 2019). "When the nonuniform expression patterns of Spry1 and Spry2 across the cancer cell lines were individually compared against this pattern, nonconformity was found." (PMID 23251157, 2012). "In sum, our observation revealed nonuniform expression patterns of Spry1 and Spry2 across the seven cancer cell lines, with the expression levels ranging from almost nil to high." (PMID 23251157, 2012). "To test this hypothesis, we suppressed both SPRY1 and SPRY2 in cancer cells by siRNA method." (PMID 26434583, 2016).
infection (2 papers, 2020 to 2021). The state of being infected such as from the introduction of a foreign agent such as serum, vaccine, antigenic substance or organism. "In U2OS as well as in MG63, both infection with Spry3 encoding and Spry1 harboring viruses results in a pronounced overexpression of the protein." (PMID 34769378, 2021). "Moreover, loss of SPRY1 triggers oncogene-induced senescence in this cell type leading to immediate cell cycle arrest after infection with the SPRY1 KO lentivirus." (PMID 33070670, 2020).
cardiac disease (1 paper, 2013). "In cardiac disease, functional assessment of miR-21 implicates PDCD4, SPRY1 or SPRY2, Phosphatase and tensin homolog, and Fas ligand as the major targets of miR-21." (PMID 23441172, 2013).
genetic disorders (1 paper, 2015). "The SPRY1 and Repeat12 crystal structures allow us to look at the detailed environments for amino acids linked to genetic disorders." (PMID 26245150, 2015).
SPRY1 also shares sentences with these, for which no sentence is quoted: colorectal cancer (4 papers); cutaneous melanoma (4); hepatocellular carcinoma (3); asthma (2); brain cancer (2); diabetes (2); ankylosing spondylitis (1); atopic dermatitis (1); attention deficit-hyperactivity disorder (1); benign prostatic hyperplasia (1); brain injury (1); cardiovascular diseases (1); cleft palate (1); colorectal adenocarcinoma (1); dental caries (1); dermatitis (1); diabetic cardiomyopathy (1); ductal carcinoma (1); dyslexia (1); esophageal squamous cell carcinoma (1); inflammation (1); inflammatory skin disease (1); invasive carcinoma (1); lupus nephritis (1); mastitis (1); metabolic disorders (1); metabolic syndrome (1); myocardial infarction (1); non-small cell lung carcinoma (1); Noonan syndrome (1).
A further 4 diseases each share a sentence with SPRY1 in 1 paper.